CD4 (CD4 molecule)
Diseases named in the same sentence as CD4 in open-access papers (continued):
Sharing a sentence is not in itself a finding about the gene and the disease.
tumor (continued). "Compared with patients of stage <II disease, tumours were of higher grade (P<0.01), greater volume (P<0.01) and increased CD4+ T-lymphocytic infiltration (P<0.05) in patients with stage >II disease." (PMID 14612901, 2003). "Tumour eradication can be obtained, however, by injection of an antibody against CD4, which is expressed on E.G7-OVA cells in vivo." (PMID 12671716, 2003). "These responses showed a strong correlation with the amount of tumour-infiltrating CD4+ lymphocytes present before treatment." (PMID 12569387, 2003). "Within the tumour tissue at baseline, a significant positive correlation between CD4 (P=0.027), CD8 (P=0.028), CD57 (P=0.007) and objective response was demonstrated." (PMID 12107842, 2002). "Median survival of patients with ⩾24 CD4 cells per mm2 tumour tissue at baseline was 22.2 months compared to 8.9 months for patients with <24 CD4 cells per mm2 tumour tissue." (PMID 12107842, 2002). "The tumour had heterogeneous HLA-DR expression with prominent CD4+ T-cell infiltration in areas positive for HLA-DR antigen, whereas relatively few cytotoxic CD8+ T-cells were present." (PMID 12232760, 2002). "Our results demonstrate that immune effector cells localise to sites of tumour in responding patients and that both CD4 and CD8 T-cell subsets are requisite for the response to IL-2 based immunotherapy." (PMID 12107842, 2002). "The identified tumour antigens, then, confirm presence of a repertoire of CD4+ cells which recognize such antigens." (PMID 12177805, 2002). "A monoclonal antibody, anti-CD4, was used to identify tumour-infiltrating lymphocytes in fine-needle aspirates before start of treatment." (PMID 11747328, 2001). "In order to identify the tumour epitopes recognized by tumour-reactive human CD4+ T cells, we combined the use of an HLA-DR4/peptide binding algorithm with an IFN-γ ELISPOT assay." (PMID 11742496, 2001). "Out of 14 patients with moderate to high numbers of infiltrating CD4+ lymphocytes, 12 achieved tumour regression." (PMID 11747328, 2001). "Based on these results and as previously shown with IFN-α therapy alone, there seems to be a need for CD4+ lymphocytes infiltrating the tumours before the start of biochemotherapy to make the treatment successful." (PMID 11747328, 2001). "A statistically significant correlation (P = 0.01) was found between the occurrence of CD4+ lymphocytes and tumour regression during biochemotherapy in patients with systemic disease." (PMID 11747328, 2001). "The cells of the interphase were depleted from tumour cells with anti-human epithelial antigen magnetic beads and then positive selection was performed with anti-CD4 or anti-CD8 magnetic beads." (PMID 10944605, 2000). "CD4 KO mice displayed a drastic reduction in the number of tumour-infiltrating macrophages and CD8+ T-cells." (PMID 10496366, 1999). "Small regressive areas, in which the histological architecture of the tumours was broken down, were found in 17 tumours with intense or moderate infiltration by CD4+ lymphocytes or CD11c+ macrophages." (PMID 9020482, 1997). "In Dukes' class A and B tumours, CD4+ lymphocytes predominated over CD4+ cells with macrophage morphology, but the latter were increasingly found in Dukes' class C and D disease." (PMID 9020482, 1997). "Ten out of 11 with moderate to high numbers of infiltrating CD4+ lymphocytes achieved tumour regression." (PMID 8845294, 1996). "In contrast, effectors derived from IL-2-activated cultures with excess CD3+ CD4+ cells lysed both autologous and allogeneic tumour target cells." (PMID 7917907, 1994). "The activated CD4+ T cells showed marked cytotoxicity against Fc receptor positive tumour cells in the presence of OKT-3 mAb." (PMID 1353365, 1992). "The transferrin receptor was found on similar numbers of CD8+ T cells in peripheral blood and among the tumour infiltrating lymphocytes while more of the CD4+ T cells infiltrating the tumour were found to carry this receptor (P = 0.034)." (PMID 2124138, 1990).
tumor (continued). "The Tac (CD 25) antigen was also on similar numbers of CD8+ T cells from both peripheral blood and the tumour but was on fewer of the CD4+ T cells in the tumour with respect to peripheral blood (P = 0.029)." (PMID 2124138, 1990). "In vivo studies have demonstrated that both innate and adaptive immune cells are essential for the anti-tumor activity of trastuzumab, involving NK cells, CD8αα + dendritic cells (DCs), adaptive CD8αβ + T cells, Type 1 CD4 + T helper (CD4 + Th1), and type I and II interferons as key players." (PMID 41582199, 2026). "However, the CD4+/CD8+ cell ratio was maintained in all tumor specimens with the percentage of CD4+ cells maintained in 5 of 8 tumors and the percentage of CD8+ cells maintained in 7 of 8 tumors." (PMID 41484629, 2026). "Furthermore, the lowest rate of Treg cells (CD3+CD4+Foxp3+) was observed in the UP+2 Gy group, suggesting that significantly fewer Treg cells remained in tumor tissues." (PMID 41355957, 2026). "CD4+/CD8+ ratios remained consistent across tumor models and treatment groups." (PMID 41495426, 2026). "Immunogenomic analyses linked high DCAF7 to CD4+ T‐cell enrichment, broad upregulation of checkpoint genes (PD‐1/PD‐L1, CTLA‐4, TIGIT), and increased tumour mutational burden, microsatellite instability and neoantigen load, suggesting an immune‐evasive phenotype." (PMID 41472554, 2026). "Strikingly, multiparametric flow cytometry analyses revealed that TGFBI was abundantly expressed by tumor cells or monocytes, and by various lymphoid cell types-including CD4+ or CD8+ T cells (including tissue-resident memory T cells), B cells, and natural killer cells-in patients with cancer." (PMID 41927343, 2026). "Moreover, the impaired secretion of cytotoxic molecules (IFN‐γ and Granzyme B) by activated CD4+ T cells was reversed by TGF‐β antibody treatment in HBx‐overexpressing tumours." (PMID 41492119, 2026). "Moreover, SEMA6D enhanced anti-tumor immunity by enhancing the infiltration of CD4+ and CD8+ T lymphocytes into the tumor microenvironment (TME)." (PMID 41735257, 2026). "Consistently, TGFBR2 knockdown restored CD4+ T cell anti‐tumour activity against DLBCL cells." (PMID 41492119, 2026). "Additionally, the ratio of CD8+ CTLs to CD4+ helper T lymphocytes in the tumor were substantially elevated in the ZCA NSs + ultrasound group, indicating robust activation of antitumor immune responses." (PMID 41424843, 2026). "Similarly, CD4+ and CD8+ T cells producing IFN-γ and TNF-α were positively associated with improved tumor control, alongside mature NK cells producing IFN-γ, whose elevated presence further supported antitumor immunity." (PMID 41522339, 2026). "Western blot analyses of tumor tissues revealed that BPA reduced the expression of marker proteins associated with M2-TAMs and Tregs, while increasing the expression of the immune-stimulatory markers CD80, GITR and CD4." (PMID 41597201, 2026). "Following sequential immunohistochemical staining for CD4+ and Foxp3+ T-cells, whole-slide scans were analyzed using QuPath software to quantify T-cells in the tumor center (TC), inner margin (IM), outer margin (OM), and peritumor zone (PT) of both pCRC and LM." (PMID 42216261, 2026). "TME profiling revealed an "immune-cold" phenotype characterized by low densities of CD4+, CD8+, and FOXP3+ T cells, CD19+ and CD20+ B cells, CD56+ and CD57+ NK cells, and CD163+ tumor-associated macrophages, alongside minimal checkpoint activity and focal fibroblast activation." (PMID 42058215, 2026). "Tumors with ICOS expression on tumor‐infiltrating CD4 and CD8 T cells may benefit from an ICOS agonist whereas tumors that express high levels of ICOS on Tregs may benefit from an ICOS inhibitor." (PMID 41474629, 2026). "Induction of CD4+ cells may also support B cells in producing tumor antigen-specific antibodies (Abs)." (PMID 41746115, 2026).
tumor (continued). "Furthermore, both CD8+ and CD4+ T cells from the DLN of Bpmel-Notch2MUT tumor-bearing mice produced IFN-γ in response to stimulation with Notch2MUT protein." (PMID 41348109, 2026). "We also identified clusters comprising CD4+ T cells, tumour cells and APCs." (PMID 41261135, 2026). "Transcriptomic analysis of the BRCA-Basal subtype, which includes most TNBC cases in The Cancer Genome Atlas (TCGA) dataset, revealed that RANKL expression correlates with increased CD4+ T-cell infiltration and lower tumor purity, indicating immune cell origin and higher metastatic risk." (PMID 41364090, 2026). "Additionally, DLBCL patients with tumour progression or death showed diminished CD4+ T cell enrichment in the TME compared with complete remission cases." (PMID 41492119, 2026). "These memory CD4+ T cells reveal a rapid and efficient response when confronting tumor invasion." (PMID 41454619, 2026). "Tumor-specific CD4+ T cells provide essential support for tumor-specific CD8+ T cells." (PMID 41348109, 2026). "Depletion of circulating CD4+ T cells with varlilumab may have abrogated benefits of inducing tumor-cognate CD4+ T cells with vaccination." (PMID 41960901, 2026). "Furthermore, TRIM3 expression correlated positively with the numbers of tumor-infiltrating CD4+ T cells, macrophages, and NK cells in LUAD and LUSC, suggesting that TRIM3 plays a role in promoting immune cell recruitment to the tumor microenvironment." (PMID 41545343, 2026). "Additionally, Tdag8-deficient mice showed a significantly increased number of macrophages in tumor tissue and an elevated CD4+/CD8+ ratio, as confirmed by IHC and flow cytometry." (PMID 42265884, 2026). "In functional assays, co-culture of sorted M-MDSCs from AT3 tumor-bearing mice with anti-CD3/anti-CD28 activated T cells resulted in a lower suppressive effect of Pgdfl/flLysMCre M-MDSCs compared to Pgdfl/fl M-MDSCs on both CD4+ and CD8+ T cells." (PMID 41535266, 2026). "CD4 + Th1 cells play a crucial role in regulating anti-tumor immunity." (PMID 41582199, 2026). "CD4+ T cells can acquire cytotoxic features under inflammatory and tumor conditions, including the secretion of granzymes, perforin, and IFN-γ, as well as the surface expression of killer ligands such as CRTAM, FasL, NKG2D, and TRAIL (CD253), which induce apoptosis in target cells." (PMID 41484912, 2026). "Concerning the tumour bed stromal components, only morphometrical quantification highlighted the prognostic role of fibrosis and inflammation, particularly when distinguishing CD4+ and FOXP3+ cells, mainly in adenocarcinomas." (PMID 41207797, 2026). "In summary, our results demonstrated that BAMBIhigh DLBCL cells may tend to suppress the anti‐tumour activity of CD4 effector, regulatory, and Th1 subsets by enhancing TGFB1‐TGFBR2 signalling in the TME." (PMID 41492119, 2026). "Moreover, NAT in Resp was associated with a spatial repositioning of CD4+ and CD8+ T cells toward tumor cells." (PMID 42253979, 2026). "However, in spleen, blood and tumour-draining lymph nodes not only CD8+ but also CD4+ T cells expressed Siglec-E." (PMID 42223497, 2026). "More extensive investigation of this case suggested that the response was driven by increased tumor infiltration of CD4+ and CD8+ cells and that this process might have been induced by TILT-123 and accelerated by the infusion of TILs." (PMID 40107242, 2025). "The density of PD-1+FOXP3+CD4+ cells and PD-L1–expressing cells was higher in group 1 than in group 2, suggesting that immunosuppressive Tregs and PD-L1 expression by the tumor may impede long-term responses to T-DXd." (PMID 39679910, 2025). "Additionally, interactions between CD90 − CD105 − endothelial cells and activated CD4 + T cells were identified as critical for repairing the tumour ecological structure." (PMID 41243106, 2025). "However, it did enhance anti-tumor T-cell responses, increasing the presence of PD-1+ CD62Llow CD4+ and CD8+ T-cells and the production of PRF1, TNF-α, and IFN-γ." (PMID 40281554, 2025).
tumor (continued). "Additionally, CD8+ T cells and CD4+ T cells were significantly increased in tumor-infiltrating lymphocytes." (PMID 41019041, 2025). "CD4 memory T cells constituted 5%, 9%, and 17% of tumor-infiltrating T cells in PR, SD, and surgical patients, respectively, suggesting that neoadjuvant therapy might encourage naïve CD4 T cell differentiation." (PMID 40541964, 2025). "Furthermore, Tregs accumulating at the tumor boundary had higher suppressive activity, with fewer CD4+ and CD8+ T cells within 100 μm compared with other Tregs, and their presence was associated with suppressed T cell proliferation." (PMID 41323783, 2025). "Conversely, memory B cells, plasma cells, naive CD4+ T cells, activated memory CD4+ T cells, regulatory T cells (Tregs), activated NK cells, M0 macrophages, activated dendritic cells, and eosinophils exhibited significant upregulation in the tumor samples." (PMID 40427030, 2025). "For instance, PD-L1-positive tumors showed a significantly higher proportion of M2 macrophages and CD4+ naïve T cells compared to PD-L1-negative tumors, and these cells were spatially closer to tumor cells, suggesting their potential influence on immune responses through paracrine mechanisms." (PMID 40867511, 2025). "The therapeutic tumor model was performed to determine the whether the CD4+ and CD8+ T cell responses induced by HCA587 SLP immunization with AddaVax and CpG 2395 could translate into anti-tumor effect in vivo." (PMID 40395227, 2025). "Published data suggest that MSCs, tumor cells, and their respective extracellular MVs possess immunosuppressive activity that inhibits cytodestructive immune responses, at least in part, through the enhancement of regulatory CD4+CD25+FoxP3+ T cell function." (PMID 41155635, 2025). "In addition, CD4+ T cells exert a range of direct and indirect functions that can contribute to tumor elimination." (PMID 40333248, 2025). "However, recent studies have shown that CD4+ T cells can also act directly as effector cells, eliminating tumor cells through mechanisms similar to the cytotoxic actions of CD8+ T cells." (PMID 40444078, 2025). "Additionally, CD4+ T cell infiltration was markedly enhanced in the metastatic tumor microenvironment, and a dramatic increase in CD8+ T cells was observed in the “HAQ/223Ra@HNPs + anti-PD-L1” group, indicating a robust cytotoxic T cell response." (PMID 41320759, 2025). "CD4+ cell infiltration differed significantly across tumor sites (p=0.011)." (PMID 39958339, 2025). "CD4‐positive T lymphocytes are also considered to play an important role in tumor immunity." (PMID 41187938, 2025). "Anti–PD-1 therapy induces CD4+ T cell–dependent lung damage in tumor-bearing aged mice." (PMID 40198121, 2025). "Furthermore, mast cells secrete chemokines such as CXCL10, CCL3, and CCL5, which recruit CD8+ and CD4+ T cells to the tumor microenvironment." (PMID 39814702, 2025). "While both CD4+ and CD8+ T cells have been identified and implicated in MDV infection and disease progression, the importance of CD8+ T cells in antiviral immunity, tumor surveillance, and immune homeostasis is well-established." (PMID 40733625, 2025). "Moreover, PDAC is characterized by tumor-infiltrating CD4+ and CD8+ T-cells; however, as PDAC progresses, the percentage of Tregs elevates within the CD4+ T-cell subset, while CD8+ T-cells shift in a decreased composition." (PMID 40906153, 2025). "While this leads to resistance to CD8+ T cell-dependent therapies like checkpoint blockade, studies reveal that in B2M-inactivated tumors, anti-tumor immunity can be alternatively mediated by activated CD4+ T cells and NK cells, uncovering a compensatory immune response pathway." (PMID 41567982, 2025). "In BRCA1/2-deficient tumors, CD4+/CD8+T cells, endothelial cells, and functional stromal cells show strengthened spatial interactions with tumor epithelial cells, and CD8+T cells are mainly distributed near the tumor cells." (PMID 40830526, 2025).
tumor (continued). "Additionally, the expression of anti-PD-1 scFv significantly reduced PD-1 expression in tumor tissues and enhanced the infiltration of CD4+ T cells and CD8+ T cells into the tumor microenvironment." (PMID 40568595, 2025). "TNBCvax provides a promising immunotherapeutic strategy capable of orchestrating a coordinated antitumor immune response, improving both CD8+ cytotoxicity and CD4+-mediated immune modulation while alleviating immunosuppressive features within the tumor microenvironment." (PMID 40969744, 2025). "Furthermore, estrogen induces a shift in the tumor microenvironment, characterized by a reduction in memory CD4+ T cells and a transition from M1 to M2 macrophage phenotypes, thus facilitating the onset and progression of EC." (PMID 40002911, 2025). "Compared to s.c. or i.m. vaccination, i.v. administration resulted in an increased frequency of Tc1 and CD4+ T helper cells in the tumor and spleen, as well as a higher ratio of CD8+ T cells to CD4+ T helper cells in the blood, suggesting successful T‐cell activation." (PMID 40125791, 2025). "In addition, tumor-specific EphA2 overexpression led to increased PD-1 expression in both CD4+ and CD8+ T cells, while CTLA-4 levels were unchanged." (PMID 40867322, 2025). "Thus, tumor-specific CD4+ T cells must be present at the sites of antigen presentation, such as the tumor-draining lymph nodes, to expand the pool of activated cytotoxic T cells." (PMID 41374956, 2025). "Circulating tumor-TCR-matched cytotoxic CD4+ T cells proliferate after PD-1 blockade." (PMID 40299576, 2025). "KIF20A expression positively correlates with CD4+ T cell infiltration and may suppress anti-tumor immunity by activating Treg cells." (PMID 41267030, 2025). "In contrast, depletion of CD4+T cells resulted in an increase in tumor volume and CBD treatment enhanced the tumor growth in CD4-depleted mice suggesting tumor growth-promoting effects of CBD in the absence of CD4+T cells and a key role of CD4+T cells in CBD-mediated anti-tumor activity." (PMID 40475776, 2025). "Once CD4+ T cells are activated, they work to recruit other immune cells to the site of tumor cells and may directly eliminate the tumor cells through the production of various cytokines." (PMID 40565098, 2025). "Furthermore, CD4+ T cells can directly interact with antigen-presenting cells to promote the presentation of tumor antigens and the formation of immune memory." (PMID 40936903, 2025). "In PDAC, CD4+ T cells were found to promote differentiation of monocytes into MHC class II anti-tumor TAMs through cognate antigen recognition and downstream CD40 and IFN-γ pathways; in turn, these MHC class II TAMs are critical promoters of anti-tumor Th1 cells and anti-tumor immunity." (PMID 40453088, 2025). "The GARP expression on the cell surface was positively correlated with the tumor population size (CD4+/CADM1+/CD7−; “N” fraction) and soluble IL-2R, suggesting that ATL cases with high GARP+ ATL cells may be clinically more aggressive." (PMID 40759773, 2025). "Notably, CCR7 expression in CD4+ T cells and B cells was varied individually in the peritumor and tumor tissues." (PMID 40685403, 2025). "This is related to the fact that γδ T cells recognize antigen in a non-MHC-restricted manner and that γδ T cells provide an early source of IFN-γ in the tumor microenvironment, γδ T cells can enhance the function of CD4+, CD8+ T cells, mature dendritic cells and activate neutrophils." (PMID 40070825, 2025). "Thus, targeting tumor-derived small EVs and their immunosuppressive cargo, such as cirmiR-20a-5p and PD-L1, presents a promising strategy to restore CD8 + and CD4 + T cell functionality and enhance anti-tumor immunity in TNBC." (PMID 40691627, 2025). "Consequently, Tregs can reduce the activity of CD8+, CD4+ T cells and Natural Killer (NK) cells, leading to tumor progression." (PMID 39075226, 2025).